TIMP1 (TIMP metallopeptidase inhibitor 1)
Diseases named in the same sentence as TIMP1 in open-access papers (continued):
Sharing a sentence is not in itself a finding about the gene and the disease.
asthma (continued). "Hoshino and colleagues found that corticosteroid treatment can decrease the deposition of subepithelial collagen through downregulation of MMP-9 and upregulation of TIMP-1 in asthma." (PMID 31547356, 2019). "HTR2C, CYP1B1, CYP19A1, ESR1, ESR2, PDR, and AR are found to be interrelated to hormonal disorders; ABCC1, NQO1, TIMP1, ADRB2, and ALOX5 are associated with asthma." (PMID 29861771, 2018). "Before the beginning of inhalation, MMP-8 was higher in asthma of moderate severity, TIMP-1 was lower and the MMP-8/TIMP-1 ratio was higher in mild and moderate asthma in comparison to healthy childeren." (PMID 27938355, 2016). "There is altered production of soluble proteins such as TGF-β1, MMPs, and a tissue inhibitor of MMPs (TIMP-1), as well as deposition of fixed proteins, such as fibronectin and tenascin in nthe airway remodeling process of asthma." (PMID 23776649, 2013). "Serum TIMP1 levels are known to be elevated in a number of arthitidites, inflammatory bowel diseases, systemic sclerosis, asthma, Parkinson’s disease and multiple sclerosis." (PMID 23555662, 2013). "Patients with asthma have an increased gelatinolytic activity linked to MMP-2 and MMP-9 and higher levels of tissue inhibitor of metalloproteinase-1 (TIMP-1; a natural inhibitor of MMPs) in their sputum." (PMID 23690670, 2013). "Studies suggest TIMP1 enhances eosinophilic airway inflammation, airway remodeling, and lung function decline in severe asthma, making it a potential marker for predicting persistent eosinophilic inflammation and poor outcomes in severe asthma." (PMID 40443529, 2025). "Many inflammatory diseases, including rheumatoid arthritis, asthma, and psoriasis, show upregulated levels of TIMP-1, suggesting that this protein could be a promising therapeutic target for the development of new anti-inflammatory treatments." (PMID 37762698, 2023). "Additionally, there were increases in the number of cells positive for ROCK1, ROCK2, TGF-β, MMP-9, MMP-12, and TIMP-1, and the percentages of isoprostane, biglycan, decorin, fibronectin, and collagen fibers, in the asthma group." (PMID 30979017, 2019). "Mediators released by activated parenchymal and inflammatory cells could induce MMPs secretion and activation, increase in MMP-9 activity, and elevated MMP-9/TIMP-1 ratios as demonstrated in mild asthma after allergen challenge in sputum and BALF." (PMID 26770019, 2015). "TIMP-1 may possibly result in the thickening process of the basement membrane in asthma." (PMID 31547356, 2019). "The involvement of Timp1 with the allergic response is very well documented; being an inhibitor of matrix metalloproteinases, it plays a central role in degradation of extracellular matrix and remodeling of tissue during inflammatory process, and appears to be involved in asthma." (PMID 21211037, 2011). "TGF-β1 is a well-established pro-fibrotic cytokine involved in subepithelial fibrosis and smooth muscle hyperplasia in asthma, while the MMP-9/TIMP-1 balance reflects extracellular matrix turnover." (PMID 41181185, 2025). "Then, the genes selected by the two methods were crossed, and finally, the key genes involved in the progression of asthma to UC (CXCL13, NOS2, TCN1, CHI3L1 and TIMP1) were obtained." (PMID 40443529, 2025). "Asthma data results show that NOS2 is resting with Mast cells (R = 0.26, p = 0.014), TIMP1 is resting with Plasma cells (R = 0.27, p = 0.011), CHI3L1 is resting with Neutrophils (R = 0.38, p = 0.00029) is positively correlated." (PMID 40443529, 2025). "The most influential nodes (Fn1, Igf1, Ccl2, C3, Timp1, Cxcl12, Ccl4, Ccr2, Spp1, C3ar1, Cat, Cyp2e1, Muc5ac, Muc5b) were selected for further validation in the OVA-induced asthma and post-asthmatic fibrosis murine model." (PMID 35625754, 2022). "There is a relationship between NGF and TIMP-1 because of the high expression of tissue inhibitors of NGF and TIMP-1 and the correlation between these parameters in asthma patients." (PMID 34502019, 2021).
asthma (continued). "Although increased level of TIMP-1 or PDGF-BB was observed among COPD and asthma patients, only a few children in our cohort had documented asthma (2 cases in the single-ARTI group, 3 cases in the multiple-ARTIs group), and no child had COPD." (PMID 31123265, 2019). "TIMP1 antagonizes tissue remodeling induced by metalloproteinase 9 and FIZZ1 is an early biomarker for tissue remodeling in asthma." (PMID 23815813, 2013). "In asthma, altered production of soluble proteins such as TGF-β1, MMPs and TIMP-1, as well as deposition of fixed proteins, such as fibronectin and tenascin, has been demonstrated to be associated with subepithelial fibrosis." (PMID 23776649, 2013). "TIMP-1 antagonizes MMP-9 activity, and a lower MMP-9/TIMP-1 ratio in sputum from untreated stable asthmatics suggests an overproduction of TIMP-1 over MMP-9 in patients with stable asthma." (PMID 33628848, 2021). "Notably, compared with asthma group, the Tetrandrine-treated group exhibited a prominent reduction of MMP-9 and TGF-β1 transcriptional level and a significant promotion of TIMP-1 mRNA." (PMID 31781316, 2019). "In our study, alveolar macrophages from chronic stable asthma patients responsive to inhaled corticosteroids released higher amounts of TIMP-1 than those of chronic unstable asthma patients who do not respond to inhaled corticosteroids or healthy subjects." (PMID 31547356, 2019). "A high expression of NGF and tissue inhibitor of metalloproteinase-1 (TIMP-1), as well as the correlation between parameters in asthma patients, indicate a possible relationship between NGF and TIMP-1, which may play an important role in asthma pathogenesis." (PMID 30939862, 2019). "In men, increases in TIMP-1 and TIMP-2 have been found in asthma and COPD." (PMID 26770019, 2015). "A higher concentration of TIMP-1 was found in human BALF of asthmatic patients compared to healthy controls; thus it might be a better marker for mild asthma." (PMID 26770019, 2015). "Since TIMP-1 shows anti-angiogenic activity by blocking the endothelial cell response to angiogenic factors and cell migration, this natural endogenous activity of TIMP-1 may be harnessed to impede angiogenic activity in asthma." (PMID 33628848, 2021). "A caveat to consider is that although TIMP1 and MMP9 enzyme activities have been associated with decline in lung function, the ratio of MMP9/TIMP1 does not necessarily correlate with the disease severity in asthma." (PMID 35387021, 2021). "TIMP-1 and TIMP-2 concentrations as well as MMP-TIMP ratios have also been studied in equine asthma showing increased levels of TIMPs in mild-to-moderate as well as severe equine asthma compared to controls and normalization of MMP-TIMP ratios under budesonide therapy." (PMID 31316303, 2019). "The high expression of tissue inhibitors of NGF and metalloproteinase-1 (TIMP-1) and the correlation between parameters of asthma patients show that there may be a relationship between NGF and TIMP-1, which may play a significant role in the pathogenesis of asthma." (PMID 34502019, 2021). "We previously presented that the absence of TIMP-1 enhances allergic lung inflammation, airway hyperreactivity (AHR), and lung remodeling in asthma in an ovalbumin (OVA) asthma model of TIMP-1 knockout (TIMPKO) mice compared to wild-type (WT) controls." (PMID 34221020, 2021). "DEX up-regulates TIMP-1 mRNA in BAL fluid cells from patients with GC-sensitive asthma, but not in cells from those with GC-R asthma." (PMID 23675190, 2010). "The ratio of MMP-9/TIMP-1 in the sputum of asthmatic patients has been shown to decrease after recovery from an acute exacerbation of asthma, which may imply that MMP9/TIMP has a negative correlation." (PMID 31547356, 2019).
Obesity (40 papers, 2012 to 2025). Accumulation of substantial excess body fat. "The association of MMP-1 levels and obesity was also verified by significant positive correlations between MMP-1 levels or MMP-1/TIMP-1 ratio and BMI/WC values in people with obesity." (PMID 34625635, 2021). "Circulating levels of TIMP-1 and -2 are increased in patients with metabolic syndrome and type 2 diabetes (T2D), while MMPs imbalance is associated with obesity and T2D." (PMID 34722599, 2021). "On the one hand, the authors reported an increase TIMP-1 levels in the serum of patients with gestational diabetes mellitus and patients with obesity and cardiovascular risk." (PMID 31581657, 2019). "Serum levels of numerous obesity-linked chemokines promoting adipocyte proliferation (TIMP-1) and adipose macrophage infiltration (CXCL1, CXCL2, CXCL12, CCL3, and CCL5) were found to be significant predictors of in vivo hippocampal TSPO signals." (PMID 27578213, 2016). "In addition, the MMP9/TIMP1 ratio has been associated with endothelial dysfunction, which is frequent in obesity-related cardiovascular disorders." (PMID 39594522, 2024). "However, when studying the association between MMP-8, TIMP-1 and disease outcomes, statistical models must be carefully adjusted for age, gender, smoking and obesity, as they seem to be major determinants of the systemic concentration of this enzyme and its inhibitor." (PMID 39917664, 2024). "Moreover, one study reported that TIMP-1 deficient mice are protected from obesity." (PMID 24736588, 2014). "For example, the stress alarmone and anorectic protein Gdf15 interact with members of two other groups, including inflammatory Cx3cl1, axon guidance-related protein (Bmp3), and the obesity-related proteins Timp1 and erythropoietin (Epo)." (PMID 39329749, 2024). "According to studies, plasma levels of TIMP1 are increased in obesity and related disorders such steatosis, which can lead to the onset of hepatic steatosis and glucose intolerance brought on by food." (PMID 38292473, 2024). "Adipose tissue-associated macrophages produce elastase MMP12—one of the targets of TIMP1 and coincidentally a marker of inflammatory response during obesity." (PMID 37432145, 2023). "Overall, the authors suggested TIMP1 is a contributing factor to diet-induced obesity, hepatic steatosis, and impaired glucose tolerance." (PMID 37445827, 2023). "Other BMs revealed to be associated with obesity-related HF are suggestive of mechanisms associated with apoptosis (TNFRSF10A), inflammation (ST6GAL1 and GAL-9) and fibrosis (MMP12, TIMP1 and QPCT)." (PMID 35945262, 2022). "In line with our results, several studies demonstrated increased TIMP-1 levels either in adipose tissue or plasma-derived from people with obesity or experimental animals." (PMID 34625635, 2021). "Our results demonstrated that there is a progressive increase in TIMP-1 levels depending on obesity status." (PMID 34625635, 2021). "TIMP expression analysis in the adipose tissues of obese mice has shown that TIMP-1 mRNA is upregulated with obesity, whereas TIMP-4 mRNA is downregulated and TIMP-2 and TIMP-3 mRNA are not significantly altered." (PMID 33020443, 2020). "The increased levels of specific ITGA5, LITAF, TIMP1 and ANXA2 mRNA isoforms in HIGH pigs is consistent with reports indicating that the overexpression of these four genes is associated with obesity and metabolic disorders in humans." (PMID 29444639, 2018). "As data still is limited, we examined diet-induced obesity, hepatic steatosis and insulin resistance in Timp1 null mice, bred on a BALB/c background." (PMID 26168159, 2015). "To elucidate the role of TIMP-1 in diet-induced development of obesity, glucose intolerance and insulin resistance we used Timp1 knockout (TKO) mice on a BALB/c background." (PMID 26168159, 2015).
Obesity (continued). "Plasma levels of tissue inhibitor of matrix metalloproteinase-1 (TIMP-1) are elevated in obesity and obesity-related disorders, such as steatosis, but the metabolic role of TIMP-1 is unclear." (PMID 26168159, 2015). "In humans, tissue inhibitor of matrix metalloproteinase-1 (TIMP-1) has been described as a biomarker of obesity, dyslipidemia, NASH, cardio-vascular disease and type 2 diabetes." (PMID 26168159, 2015). "The study has also reported enhanced serum concentrations of TIMP-1 in response to obesity." (PMID 40699617, 2025). "Accordingly, we want to assess the profile of MMPs and TIMPs gene expression (MMP-2, 9, 12, 14, TIMP-1,2) in peripheral leukocytes, and plasma levels of MMP-2, 9, TIMP-1,2 of children with simple obesity to find out if they correlate with obese-related parameters." (PMID 38541059, 2024). "MMP1a mRNA and protein levels were elevated in the knee cartilage of newborn male 7-day mice in the maternal obesity group relative to those in the control group (p < 0.05, p < 0.01, respectively), while TIMP1 mRNA and protein expression levels decreased (p < 0.001, p < 0.05, respectively)." (PMID 35327669, 2022). "The increase in TIMP-1 levels in people with overweight could be an early predictor for obesity and obesity-related cardiovascular diseases." (PMID 34625635, 2021). "Another study demonstrated that obesity was observed in mice with deletion of TIMP-1 gene." (PMID 34625635, 2021). "The role of TIMP-1 in obesity development was also supported by experimental studies." (PMID 34625635, 2021). "On the other hand, there are some contradictory results regarding on TIMP-1 levels in obesity." (PMID 34625635, 2021). "However, Timp1 encoding for an inhibitor of MMPs and Lox encoding for an ECM cross-linking enzyme, were deregulated during the response to the trauma in obesity." (PMID 32848828, 2020). "In obesity, Timp1 (tissue inhibitor of metalloproteinases 1), Spp1 (osteopontin/secreted phosphoprotein 1), PAI-1 (plasminogen activator inhibitor-1) and Igfbp3 (insulin-like growth factor-binding protein 3) significantly increase in adipose tissue and contribute to the insulin resistance." (PMID 31576964, 2020). "In addition, sex, smoking, and obesity are associated with both MMP-8 and TIMP-1 concentrations." (PMID 39917664, 2024). "However, except for negative correlation between plasma MMP-9 and total cholesterol there were no other associations between the expression of MMP9/TIMP-1 axis and the obesity phenotype parameters." (PMID 38541059, 2024). "In our experimental model, we found several other circulatory molecules that were increased mainly in the Pso–obesity group, like ICAM-1 and TIMP-1." (PMID 40869018, 2025). "TIMP-1 and TIMP-2 plasma levels are increased in patients with metabolic syndrome and their levels correlate with obesity indices including BMI, waist circumference and metabolic parameters." (PMID 38541059, 2024). "Altogether, this study demonstrates that TLR2 mediates collagen accumulation and pro-inflammatory cytokines’ activation in WAT during diet induced obesity, involving MMP1 and TIMP1 imbalanced expression." (PMID 37445827, 2023). "TGF-β expression is positively correlated with the expression of TIMP-1, TIMP-3, and TIMP-4 in adipose tissue of people with obesity." (PMID 37383542, 2023). "Although the correlations between most of the DEGs we identified in this study and obesity are well-established, such as SERPINE1, PLAUR, CA3, and TIMP1." (PMID 35894174, 2022). "Among these TIMPs, especially TIMP-1 and TIMP-2 gain importance in obesity-related cardiovascular diseases." (PMID 34625635, 2021).
Obesity (continued). "Hepatic TIMP1 and TIMP2 levels are elevated in obesity-related non-alcoholic fatty liver disease (NAFLD), and TIMP1 has been shown to mediate HFD-induced hepatic steatosis in mice." (PMID 28740132, 2017). "MMPs are inhibited by endogenous tissue inhibitors (TIMPs), and we here demonstrated upregulation of tissue inhibitors of metalloproteinases TIMP-1 and TIMP-4 with obesity." (PMID 22748184, 2012). "Obesity induced adipose tissue cytokine expressions, the most highly upregulated cytokines being IL-1ra, IL-2, IL-16, MCP-1, MIG, RANTES, C5a, sICAM-1 and TIMP-1." (PMID 22748184, 2012). "However, a contradictory finding has been reported in a twin cohort on obesity and MMP-8 levels, where MMP-8 concentration and the MMP-8/TIMP-1 molar ratio increased with increasing weight." (PMID 39917664, 2024). "In obesity, increased TGF-β signalling has been suggested to exert pro-fibrogenic actions by stimulating the expression of tissue inhibitors of metalloproteases (TIMPs), including TIMP-1, TIMP-3, and TIMP-4, and connective tissue growth factor (CTGF)." (PMID 37383542, 2023). "Our results exhibited that TIMP-1 levels were markedly and gradually increased in people with obesity as compared to overweight and non-obese people." (PMID 34625635, 2021). "Significantly increased levels of TIMP-1 were found in people with obesity when compared to non-obese people (P < 0.001)." (PMID 34625635, 2021). "However, in two animal models of genetic obesity (ob/ob and db/db) and in a HFD model, while mRNA levels for MMP2, MMP3, MMP12, MMP14, MMP19, and TIMP1 are robustly induced, MMP7 (and MMP3) transcripts are markedly reduced in obese visceral adipose tissue compared to lean tissue." (PMID 37445827, 2023). "Interestingly, plasma levels of TIMP-1 and JE cytokines were higher in obese CS-HFFC further supporting the notion that the inflammatory microenvironment may be driving tumor progression in the context of obesity." (PMID 35994501, 2022).